DNMT1 (DNA methyltransferase 1)
Diseases named in the same sentence as DNMT1 in open-access papers (continued):
Sharing a sentence is not in itself a finding about the gene and the disease.
lupus (continued). "One study found that the overexpression of miR-125 correlates to the reduction of DNMT1 protein expression in lupus CD4+ T cells, and another study reported overexpression of miR-126 in healthy donor CD4+ T cells that led to hypomethylation and overexpression of genes CD11a and CD70." (PMID 25566322, 2014). "Downregulation of DNMT1 in CD4+ T cells contributes to lupus autoreactivity by inducing T cell DNA hypomethylation; this results in the overexpression of autoimmunity-associated genes including lymphocyte function-associated antigen 1 (LFA-1 or CD11a) and CD70." (PMID 23983769, 2013). "The observation that inhibiting ras-MAPK signaling decreases DNMT1 expression to the same extent as is observed in lupus and that this decrease correlates with DNA hypomethylation in vitro and in vivo, suggests that the defect in DNMT1 is the primary reason for DNA hypomethylation in SLE." (PMID 23596493, 2013). "Intriguingly, DHA exhibits context-dependent epigenetic effects: in systemic lupus erythematosus (SLE) models, it upregulates DNMT1 and enhances global DNA methylation." (PMID 40697663, 2025). "DNMT1 is required to maintained CpG methylation and aberrant gene silencing in multiple physical process and diseases, including cell differentiation, T cell development and function, differentiation and function of stem cells, systemic lupus erythematosus, tumor initiation and progression." (PMID 27286455, 2016). "Consistent findings were reported for miR-126 and miR-29b in lupus: these miRNAs are also elevated in SLE T cells and have been found to negatively regulate DNMT1 further reinforcing that multiple miRNA pathways converge on the DNA methylation machinery." (PMID 41376628, 2025). "Reduced expression/activity of DNMT1 and/or DNMT3a/3b has been identified in the PBMCs or CD4+ T cells of human patients with lupus, which contributed to the DNA hypomethylation in human lupus cells." (PMID 38153351, 2023). "There was a significantly elevated expression of Dnmt1 and Dnmt3b, as well as Tet1 and Tet2, in CD4+ T cells of three different lupus-prone mouse strains compared to controls." (PMID 38153351, 2023). "In systemic lupus erythematosus (SLE), the overexpression of miR-21 and miR-148a in CD4+ T cells contributes to DNA hypomethylation by repressing DNMT1." (PMID 37239435, 2023). "Increased miR-29b in lupus T cells suppressed SP1, a positive regulator of DNMT1, leading to DNA hypomethylation." (PMID 34062726, 2021). "Nevertheless, other studies demonstrated unchanged DNMT1 and even increased DNMT3a/3b expression in human lupus PBMCs or CD4+ T cells, despite the consistency of DNA hypomethylation in these lupus cells." (PMID 34062726, 2021). "In lupus CD4+ T cells, the up-regulated miR-21 can suppress the expression of DNA methyltransferase 1 and enhance DNA hypomethylation." (PMID 31163082, 2019). "In systemic lupus erythematosus (SLE), RFX1 downregulated IL17A, CD70, and CD11a expression by recruiting DNMT1, HDAC1, and SUV39H1 to alter epigenetic modifications in CD4+ T cells from patients with lupus." (PMID 30857550, 2019). "The PP5 over-expression is consistent with the decreased Dnmt1 levels and increased KIR, perforin, CD40L, CD70, and CD11a expression seen in CD4+CD28+ T cells from lupus patients." (PMID 28239687, 2016). "Studies on lupus CD4+ T cells have shown that UV-B radiation inhibits SIRT1-mRNA and protein expression by activating AhR and suppressing DNMT1 activity in CD4+ T cells by binding upstream of the SIRT1 promoter translation initiation site, thus mitigating the progression of the pathological process." (PMID 37483618, 2023). "As indicated from the results, circ_0012919 reduction enriched the expression of DNMT1, decreased the expressions of CD70 and CD11a, and reversed the DNA hypomethylation of CD11a and CD70 in CD4+ T cells of systemic lupus erythematosus (SLE); however, it was reversible by DNMT1 reduction." (PMID 32665846, 2020).
lupus (continued). "Dnmt1 levels are normally upregulated by signals transmitted through the ERK and JNK pathways as T cells enter mitosis, and ERK pathway signaling is decreased in T cells from active lupus patients, contributing to the low Dnmt1 levels." (PMID 30764520, 2019). "Interestingly, in lupus CD4+ T cells, it has been shown that miR-29b inhibits DNMT1 by indirectly binding to Sp1 which is a permissive regulator of DNMT1." (PMID 28785369, 2017). "PP5 expression is also increased by oxidative stress, and may similarly contribute to lupus flares by suppressing ERK pathway signaling, leading to decreased Dnmt1 expression and subsequent over-expression of pro-inflammatory genes." (PMID 28239687, 2016). "Dnmt1 levels, as well as ERK pathway signaling are decreased in CD4+ T cells from lupus patients." (PMID 28239687, 2016). "T cells from patients with active lupus manifest increasedmitochondrial oxidative phosphorylation and reactive oxygen species (ROS).Oxidative stress of CD4+ T cells results in decreased levels of DNMT1,DNA demethylation, and upregulation in expression of several genes." (PMID 33097564, 2020). "CD4+CD28− stress-induced, PP5 overexpressing T cells have decreased ERK and JNK pathway signaling, low Dnmt1 levels, and overexpress methylation sensitive genes including KIR2DL4, CD70 and perforin, similar to the epigenetically altered CD4+CD28+ T cells from patients with active lupus." (PMID 28239687, 2016). "Real-time PCR analyses of DNMT1, DNMT3A and DNMT3B in peripheral blood mononuclear cells from a cohort of African American and European American lupus and non-lupus women were conducted." (PMID 23054340, 2013).
cervical carcinoma (48 papers, 2011 to 2026). A carcinoma arising from either the exocervical squamous epithelium or the endocervical glandular epithelium. "Overexpression of DNMT1, 3A and 3B has been reported in cervical cancer cells and is associated with disease progression." (PMID 31766427, 2019). "As reported by Szyf, DNMT1 inhibited the transcription of tumor suppressor genes and facilitated the formation of tumorigenesis, which linked to the development of cervical cancer." (PMID 21999220, 2011). "In a word, DNMT1 represents an important potential diagnostic and therapeutic target for cervical cancer." (PMID 21999220, 2011). "Moreover, the methylation status of the DNMT1 promoter could serve as a non-invasive diagnostic biomarker in cervical cancer." (PMID 41226543, 2025). "The HeLa cells (an adenocarcinoma cervical cancer cell line) display DNMT1 overactivity, resulting in the hypermethylation of these genes and downregulation of their expression." (PMID 40510497, 2025). "JAK inhibitors combined with DNMT1 inhibitors can promote cervical cancer tumor cells to undergo apoptotic cell death." (PMID 39160604, 2024). "EDN3 silencing mediated by methylation can be blocked by 5-Aza, a DNMT1 inhibitor, treatment in cervical cancer cell lines." (PMID 36824133, 2023). "EDN3 silencing mediated by methylation can be blocked by 5-Azacytidine (5-Aza), a DNA methyltransferase 1 (DNMT1) inhibitor, treatment in cervical cancer cell lines." (PMID 36824133, 2023). "Secondly, we the measured the expression of EDN3 after 5-Azacytidine (5-Aza), a DNMT1 inhibitor, treatment in cervical cancer cell lines to investigate the effect of methylation on EDN3 expression." (PMID 36824133, 2023). "miRNA-148b suppressed cell cycle progression and facilitated cell apoptosis by regulating DNMT1 in cervical cancer and endometrial cancer in a caspase-3 dependent manner." (PMID 36959680, 2023). "Overall, these data suggest a potential contribution of BARF1 to EMT in cervical cancer cells, although further studies investigating the DNMT1/E-Cadherin axis and/or the expression profile of other EMT-related molecules are strongly recommended." (PMID 35630333, 2022). "HPV oncoproteins were shown to modulate DNMT1 levels and some studies have been developed to identify HPV-associated alterations of DNA methylation in cervical cancer." (PMID 34298834, 2021). "In regards to its potential epigenetic activity, eugenol induced promoter hypomethylation of LIMD1 and P16 genes following the reduced expression of DNMT1 in the human cervical cancer cell line Hela." (PMID 34835969, 2021). "Together, these data suggest that the level of DNMT1 expression also can affect LINE expression in cervical cancer." (PMID 34298727, 2021). "In cervical cancer patients, DNMT1 was expressed in more than 70% of cancer cells, whereas only 16% of normal cells expressed DNMT1." (PMID 31871779, 2019). "DNA methyltransferase activity was upregulated by the binding of HPV-16 E7 and DNMT1, thus, increased the hypermethylation in many TSGs led to the development of human cancer of cervix." (PMID 29845022, 2018).
cervical carcinoma (continued). "The aim of this research was to investigate the relationship between DNMT1 and abnormal methylation of tumor suppressor genes and malignant phenotype in cervical cancer." (PMID 21999220, 2011). "In our study, we detected the demethylation and re-expression levels of seven cervical cancer suppressor genes with DNMT1 silencing in Hela and Siha cells." (PMID 21999220, 2011). "A study revealed that DNMT1 knockdown increases the proportion of cells in the G0/G1 phase, decreases the proportion in the S phase, promotes apoptosis, and reduces cell proliferation in HeLa and SiHa cervical cancer cells." (PMID 41226543, 2025). "Finally, DNMT1 plays a key role in maintaining cervical cancer stem cell-like cells (CCSLCs) through the miR-342-3p/DNMT1/FoxM1 regulatory axis." (PMID 41226543, 2025). "Reactivation of PAX1 due to promoter hypomethylation has been achieved through silencing of DNMT1 in Hela and Siha cell lines, suggesting DNMT1 might be the methytransferase responsible for the hypermethylation level of PAX1 in cervical cancer cells." (PMID 36393845, 2022). "Additionally, the HPV E7 oncoprotein has been reported to form a complex with DNMT1 and DNMT1 is upregulated in HPV-associated OPSCC and cervical cancer." (PMID 33920277, 2021). "In summary, our findings describe retroelement expression profiles in cervical cancer and their association with endogenous factors, such as IL20 family genes and DNMT1, which showed a significant correlation with up- and downregulation of L1 expression, respectively." (PMID 34298727, 2021). "The activity of DNA methyltransferase 1 (DNMT1), the major methyltransferase responsible for maintaining DNA methylation patterns following cellular replication, is elevated in many tumors, including cervical cancers." (PMID 32570816, 2020). "HPV-16 E6 was previously found to upregulate DNMT1 in human cervical cancer cells." (PMID 28077801, 2017). "Currently, functions and mechanisms of DNMTs in cervical cancer cells remained unclear, and whether DNMT1 and DNMT3b act synergistically or through other ways exploration efforts were still required study." (PMID 21999220, 2011). "DNMT1 silencing in cervical cancer cells could induce re-expression of most tumor suppressor genes by demethylating its promoter region, and co-silencing of DNMT1 and DNMT3b might perform a greater inhibitory effect on tumorigenesis." (PMID 21999220, 2011). "The aim was to elucidate the relations between DNMT1 and abnormal methylation of these genes' promoter as well as the malignant phenotype of tumor cells, which might contribute to the investigations of functions and regulation roles of DNMT1 in cervical cancer." (PMID 21999220, 2011). "Our experimental results demonstrate that methylation status of DNMT1 can influence several important tumor suppressor genes activity in cervical tumorigenesis and may have the potential to become an effective target for treatment of cervical cancer." (PMID 21999220, 2011). "On the other hand, knockdown of DNMT1 and DNMT3B reduces methylation of the SORBS3-β promoter, thereby increasing its expression in SiHa cervical cancer cells." (PMID 41226543, 2025). "The study revealed that human papillomavirus infection disrupts the epigenetic balance of DNMT1 and TET1, leading to increased DNMT1 expression and decreased TET1 expression during cervical cancer development." (PMID 40520993, 2025). "Upon inhibiting M. SssI (DNMT1 analog), these two substances inhibited DNMT1, thereby hypomethylating and reactivating the FANCF promoter and inhibiting cervical cancer progression." (PMID 32328088, 2020). "Previous studies have shown that miR-29a was low expression in cervical cancer, as a tumor suppressor, miR-29a can target multiple genes, such as CDC42, HSP47, SIRT1 and DNMT1." (PMID 33150075, 2020).
cervical carcinoma (continued). "Previous studies show that SFN decreased DNMT1, DNMT3A, and DNMT3B expression, leading to global DNA hypomethylation in human breast, prostate, and cervical cancer cell lines." (PMID 32878338, 2020). "In fact, DNA methyltransferase 1 (DNMT1), a major enzyme for DNA methylation, was found to be overexpressed in human cervical cancer." (PMID 28077801, 2017). "Recent studies have also demonstrated the toxicity of TCS on cervical cancer CaSki cells, and that TCS plays a role in demethylation by inhibiting DNA (cytosine-5)-methyltransferase 1 (DNMT1) enzyme activity and DNM1 mRNA and protein expression in CaSki cells." (PMID 23377374, 2013). "miR-148a also repressed proliferation of bladder cancer cells by establishing a positive feedback loop between ERBB3/AKT2/c-myc signaling and DNMT1 or by regulating expression levels of DNMT1 and undifferentiated embryonic cell transcription factor 1 (UTF1) in cervical cancer cells." (PMID 36959680, 2023). "Altogether our results show that G extract mediates its growth inhibitory effects on human cervical cancer HeLa cell line likely via the activation of a p16INK4A -dependent cell cycle checkpoint signalling pathway orchestrated by UHRF1 and DNMT1 down-regulation." (PMID 23688286, 2013). "The aim of this study was to determine, in HeLa cervical cancer cell line, whether Limoniastrum guyonianum aqueous gall extract and luteolin, one of the most common flavonoids, could target UHRF1 and DNMT1 expression with subsequent cell cycle arrest and apoptosis via up-regulation of p16INK4A gene." (PMID 23688286, 2013).
glioblastoma (48 papers, 2011 to 2026). The most malignant astrocytic tumor (WHO grade IV). "In summary, we show that downregulation of CBX7 in glioblastoma is caused by promoter hypermethylation that is mediated by DNMT1 and DNMT3A." (PMID 39988672, 2025). "It is also noteworthy that methylation of DNMT1 is significantly up-regulated in glioblastomas, whereas loss-function of DNMT1 was previously correlated with increased cell apoptosis and suppressed cell invasion." (PMID 35255904, 2022). "RCC2 promotes radio-resistance and propagation in glioblastoma by transcriptionally stimulating DNMT1 in a STAT3-dependent manner." (PMID 38008751, 2023). "Other studies have shown that the MEG3 promoter can be hyper-methylated by DNA methyltransferase 1 (DNMT1) in glioblastoma tissue, thereby completely silencing the gene." (PMID 34316694, 2021). "miR-152 targeting DNMT1 inhibits the development of endometrial cancer, glioblastoma, and lymphomas." (PMID 33718161, 2021). "The results concluded that phospho-c-Jun controls DNMT-1 expression and regulates DNA methylation in glioblastoma." (PMID 33670008, 2021). "The JAK-STAT pro-survival pathway is closely linked to cancer cell survival, and a recent study suggested that p-STAT, a downstream JAK-STAT pathway protein, bound to the promoter of DNMT1 and triggered tumor progression in glioblastoma." (PMID 34439091, 2021). "In glioblastoma, RCC2 is implicated in tumor proliferation, tumorigenicity, and promoting radio-resistance by activating DNA methyltransferase 1 (DNMT1) transcription in a p-STAT3 dependent manner." (PMID 33521058, 2020). "On the other hand, miRNA-148 promotes cell growth and inhibits cell death in glioblastoma.We demonstrated that DNMT1, one of the key enzymes of DNA methylation, is regulated in a miRNA dependent manner by miRNA-148a." (PMID 31564251, 2019). "For example, miR-148-3p inhibited the growth of glioblastoma by targeting DNMT1 and PCa cell growth in vivo." (PMID 31455210, 2019). "We then sought to validate the relationship between c-Jun phosphorylation and DNMT1 in patient-derived glioblastoma cells." (PMID 28036297, 2017). "Our findings suggest that phospho-c-Jun activates an important regulatory mechanism to control DNMT1 expression and regulate global DNA methylation in Glioblastoma." (PMID 28036297, 2017). "Nevertheless, since the highly methylated glioblastoma (G-CIMP) are mostly proneural, we would mostly expect association between DNMT1 expression and DNA methylation in proneural samples." (PMID 28036297, 2017). "We recently linked DNMT expression to TMZ resistance and glioblastoma cell survival, and further showed that DNMT1 downregulation led to changes in gene expression." (PMID 26337869, 2015). "Another mechanistic approach by which DNMT1 may contribute to glioblastoma pathogenesis is the methylation of the miR‐152 promoter." (PMID 40387409, 2025). "Although previous studies have reported hypermethylation of SPINT2 and its tumor-suppressive effects in glioblastoma, its role in senescence and direct regulation by DNMT1 were unknown." (PMID 40838961, 2025). "Guang-Yuh Chiou and his co-workers found that IL6 could induce DNA methyltransferase 1 expression leading to hypermethylation of the miR142-3p promoter which influenced Sp1-binding motif in the promoter to contribution to glioblastoma tumorigenesis." (PMID 35541892, 2022). "As our future goal, we thus aim to conduct an academic phase II clinical study to evaluate the safety and efficacy of the combination of DNMT1 inhibitor azacytidine and lomustine in recurrent glioblastoma patients, whose life expectancy with current treatments is approximately 7.8 months." (PMID 34645858, 2021). "Since G-CIMP tumors have been described as less aggressive and characterized by a better outcome, the c-Jun/DNMT1 pathway could potentially serve as a new target for the treatment of glioblastoma." (PMID 28036297, 2017).